EGFR (epidermal growth factor receptor)
Diseases named in the same sentence as EGFR in open-access papers (continued):
Sharing a sentence is not in itself a finding about the gene and the disease.
perihilar cholangiocarcinoma (1 paper, 2017). "In preliminary experiments it was discovered that epidermal growth factor receptor (EGFR), a receptor overexpressed in a multitude of cancers including perihilar cholangiocarcinoma, was afflicted by PDT with ZnPC-liposomes." (PMID 27803950, 2017).
peritonitis (1 paper, 2025). Inflammation of the peritoneum (tissue that lines the abdominal wall and covers most of the organs in the abdomen). "Baicalin is associated with the suppression of inflammatory factor expression, likely via modulation of the ADAM17/EGFR axis, and the improvement of the peritonitis injury caused by GPS infection in piglets." (PMID 40867785, 2025). "In our study, baicalin alleviated the ADAM17/EGFR axis-induced inflammatory injury of peritonitis in PPMCs and piglets infected by GPS, which means that targeting ADAM17 may be the key to alleviating the inflammatory injury of piglet peritonitis." (PMID 40867785, 2025). "Therefore, this study aimed to elucidate the molecular mechanism by which baicalin alleviates GPS-induced peritonitis in piglets, specifically focusing on the role of the ADAM17/EGFR signaling axis." (PMID 40867785, 2025).
peroxisomal disease (1 paper, 2016). A group of congenital disorders of lipid metabolism, caused by loss of the normal peroxisomes. "This study was carried out to investigate the effect of PA on NOX and EGFR in vascular smooth muscle cells, to understand cellular and molecular mechanisms of PA-induced pathogenesis in peroxisomal disorders and development of cancer." (PMID 27287039, 2016). "An increase in phosphorylation of EGFR by PA and attenuation of PA-induced NOX activity by EGFR inhibitor provide an important insight into molecular mechanism of PA's role in pathogenesis of some peroxisomal diseases and cancers." (PMID 27287039, 2016).
placental diseases (1 paper, 2021). "In addition, aberrant expressions of EGF and EGFR are associated with trophoblast cell invasion-related placental diseases." (PMID 34620174, 2021).
plantar fibromatosis (1 paper, 2017). A superficial fibromatosis arising from soft tissue of the plantar regions. "With a possible role in epidermal growth factor receptor signaling, ASTE1 may contribute to the increased risk for palmar/plantar fibromatosis in patients with Lamin A/C haploinsufficiency." (PMID 29104234, 2017). "With the possible role of ASTE1 in EGFR signaling, the complex pathway with significant roles in cell–cell communication, cell fate, and proliferation, our findings raise the possibility that ASTE1 c.230T>C (p.Val77Ala) may result in susceptibility to palmar and plantar fibromatosis in our family." (PMID 29104234, 2017).
pneumococcal infection (1 paper, 2023). Infections with bacteria of the species streptococcus pneumoniae. "Our previous study showed that NE activity increased to an average of 431.6 mU/ml in BALF of pneumococcal-infected mice, suggesting that increased NE activity because of pneumococcal infection may degrade not only EGFR but also EGF and inhibit alveolar epithelial repair." (PMID 37119853, 2023).
pneumococcal pneumonia (1 paper, 2023). A febrile disease caused by STREPTOCOCCUS PNEUMONIAE. "In summary, we demonstrated a novel mechanism of severe pneumococcal pneumonia, in which NE degrades EGFR expressed on alveolar epithelial cells and inhibits alveolar epithelial repair." (PMID 37119853, 2023). "Fragments of EGFR ECD were detected in bronchoalveolar lavage fluid from pneumococcal pneumonia mice, and the percentage of cells positive for a cell proliferation marker Ki67 in lung tissue was reduced." (PMID 37119853, 2023). "To confirm that EGFR degradation by NE occurs in lung tissue, we analyzed the amount of EGFR in lung tissues from model mice of pneumococcal pneumonia." (PMID 37119853, 2023). "In this study, we examined whether NE degrades EGFR expressed in cells, using alveolar epithelial cells and a mouse model of pneumococcal pneumonia." (PMID 37119853, 2023). "Therefore, we hypothesized that aberrations in molecules related to tissue repair contribute to the exacerbation of pneumococcal pneumonia and analyzed the interaction between EGFR and NE." (PMID 37119853, 2023). "Therefore, abnormal EGFR signaling might be involved in exacerbating pneumococcal pneumonia." (PMID 37119853, 2023).
proliferative diabetic retinopathy (1 paper, 2023). Advanced retinopathy due to diabetes mellitus characterized by the formation of new vessels in the retina. "Previous studies indicate an autocrine/paracrine role for EGF, TGF-α, HB-EGF, and EGFR in proliferative diabetic retinopathy." (PMID 37936170, 2023).
prostatic hyperplasia (1 paper, 2023). "Another result from this study showed that treatment with isoflavones (ERβ agonists) inhibited finasteride-induced EGFR nuclear translocation during prostatic hyperplasia (BPH) treatment." (PMID 37361598, 2023).
prostatic intraepithelial neoplasia (1 paper, 2024). "Antagonism of the epidermal growth factor receptor (EGFR) in cancer cells disrupts normal epithelial endorsement and succession, limiting normal cell transformation into persistent and metastatic cancer cells via dysplasia to high-grade prostatic intraepithelial neoplasia (HGPIN)." (PMID 39473624, 2024).
prostatic small cell carcinoma (1 paper, 2025). "Potential molecular targets—such as C-kit, EGFR, BCL2, and CD56—identified in prostatic small cell carcinoma warrant further investigation in ureteral SCNEC." (PMID 41257218, 2025).
pulmonary adenoid cystic carcinoma (1 paper, 2015). "The data presented in this work suggest that EGFR, KRAS, BRAF, ALK, PIK3CA, PDGFRA, and DDR2 may not be driver genes in primary pulmonary adenoid cystic carcinoma." (PMID 26373952, 2015).
pulmonary edema (1 paper, 2022). Accumulation of fluid in the lung tissues causing disturbance of the gas exchange that may lead to respiratory failure. "We found that ibrutinib effectively suppressed poly I:C- and LPS-induced pulmonary edema, pro-inflammatory cytokine release, histopathological changes, neutrophil aggregation, lymphocyte aggregation, and activation of the BTK-, FLT3-, and EGFR-related signaling pathways." (PMID 36362264, 2022).
pyometra (1 paper, 2024). "In contrast, increased gene and protein expression of the epidermal growth factor receptor (EGF-R) have been demonstrated in dogs with pyometra." (PMID 39457917, 2024).
Refsum disease (1 paper, 2016). Refsum disease, biochemically characterised by phytanic acid accumulation, belongs to the group of leucodystrophic diseases. "Our findings that PA transactivates EGFR and induces NOX activity in vascular smooth muscle cells provide new insights into molecular mechanisms of PA’s role in cancer and Refsum disease." (PMID 27287039, 2016).
retinal degeneration (1 paper, 2025). Degeneration of the retina. "Consistent with the role of the Ezrin/EGFR/TSC complex axis in lysosomal biogenesis and function, alteration of this molecular network alters autophagy in vivo in Medaka fish, resulting in retinal degeneration." (PMID 39937579, 2025). "Consistently, Medaka fish deficient for Ezrin exhibit defective endo-lysosomal pathway, attributable to the compromised EGFR/AKT signaling, ultimately leading to retinal degeneration." (PMID 39937579, 2025).
Retinal dysplasia (1 paper, 2025). Abnormal growth and differentiation, structure and appearance of the retina present from birth. "Likewise, aged YAP+/− mice, created using PKG-Cre and YAP flox/+ mice, exhibit impaired cone visual function due to retinal dysplasia and late-onset cone degeneration caused by the deficiency of YAP and the epidermal growth factor receptor (EGFR)." (PMID 39503968, 2025).
rheumatic diseases (1 paper, 2018). "Although little is known about the involvement of neuregulin in the pathogenesis of rheumatic diseases, it has been reported that EGFR is expressed in fibroblasts and vascular endothelial cells and that EGFR signaling induces FLS proliferation and cytokine production in patients with RA." (PMID 30886985, 2018).
rhinitis (1 paper, 2022). An inflammation of the mucous membrane lining the nose, usually associated with nasal discharge. "The results of the present study confirmed that after YPFS treatment of AR mice and EGFR reduction, the expression of inflammatory factors in the OVA-induced AR group decreased, and rhinitis symptoms were alleviated, suggesting that EGFR reduction benefits AR treatment." (PMID 36017263, 2022).
sebaceous carcinoma (1 paper, 2022). "For sebaceous carcinoma, tumor sequencing revealed RAR-β, androgen receptor, mTOR, and EGFR as the potential investigational approaches." (PMID 35205753, 2022).
sebaceous tumors (1 paper, 2021). "EGFR mutations in sebaceous tumors are described in previous studies." (PMID 34065301, 2021).
seborrheic keratosis (1 paper, 2025). A common benign skin neoplasm usually affecting older individuals. "While its pathophysiology is not fully understood, factors like human growth factor, Epidermal Growth Factor alpha, and the Epidermal Growth Factor Receptor are believed to contribute to seborrheic keratosis development." (PMID 40142228, 2025).
secondary hyperparathyroidism (1 paper, 2022). Overproduction of parathyroid hormone in response to influence external to the parathyroid glands. "The A431 cell did not originate from parathyroid gland, but it displayed a similar EGFR/TGF-α feed-forward circuit to that reported in secondary hyperparathyroidism." (PMID 36267284, 2022).
Sjögren’s Syndrome (1 paper, 2022). "No clinical trials were found to evaluate drugs with EGFR as a target and only one clinical trial has evaluated a drug with NFKB1 as a target for Sjögren’s Syndrome (NCT00001599)." (PMID 35268532, 2022).
skin fragility (1 paper, 2021). "This work provides insight into how EGFR regulates adhesion signalling and shed light on how disruptions in EGFR signalling lead to the development of skin fragility." (PMID 34375550, 2021).
small cell carcinoma of bladder (1 paper, 2015). "Epidermal growth factor receptor (EGFR) protein expression and gene amplification were evaluated in small cell carcinoma of bladder, and presence of these was correlated with the pathological stage of this tumor." (PMID 26788399, 2015).
small intestinal adenoma (1 paper, 2011). "We observed that exposure to chronic IGF1R inhibition may delay small intestinal adenoma growth, whereas combined IGF1R/EGFR blockade suppresses growth relative to single agent treatments." (PMID 21811251, 2011).
squamous cell and ovarian carcinomas (1 paper, 2018). "Current studies have demonstrated that intracellularly-localized EGFR is associated with poor prognosis, increased malignant potential, and decreased disease-free survival rates of patients with squamous cell and ovarian carcinomas." (PMID 29464085, 2018).
staphylococcal pneumonia (1 paper, 2017). Pneumonia caused by infections with bacteria of the genus staphylococcus, usually with staphylococcus aureus. "SpA activates and controls the pro-inflammatory response by interacting with the TNF receptor 1 and the epidermal growth factor receptor on airway epithelial cells, which contributes to the pathogenesis of staphylococcal pneumonia." (PMID 28536677, 2017).
Stillbirth (1 paper, 2022). Death of the fetus in utero after at least 22 weeks of gestation. "EGFR knockout mice were stillbirth or lived only up to 6–8 days, displaying epithelial alterations and dysfunctions in several tissues, such as lungs and intestine." (PMID 34955078, 2022).
synovitis (1 paper, 2025). Inflammation of a synovial membrane. "The elevated EGFR expression in our OA samples may therefore represent late-stage reactivation associated with advanced synovitis." (PMID 41463004, 2025).
systemic inflammatory response syndrome (1 paper, 2026). SIRS is a serious condition related to systemic inflammation, organ dysfunction, and organ failure. "Regarding EGF, its administration attenuated lung inflammation and injury, probably through activating EGFR, leading to the suppression of NF-κB signaling, promotion of cell proliferation, and inhibition of apoptosis, as well as the prevention of systemic inflammatory response syndrome." (PMID 41596232, 2026).
tendinopathy (1 paper, 2024). "Specifically, CTHRC1 interacts with EGFR and subsequently activates the MAPK signaling pathway to promote TSPC proliferation, migration, and tenogenic differentiation, thus promoting tendon regeneration and attenuating tendinopathy." (PMID 39540237, 2024).
Thrombus (1 paper, 2017). "Thrombus has not been reported as an adverse event in patients receiving EGFR-TKIs." (PMID 29169381, 2017).
Trichiasis (1 paper, 2024). Inversion and rubbing of the eyelashes against the globe of the eye. "A retrospective study on ocular toxicities among 69 patients treated with EGFR inhibition for malignancy found that 22 patients developed MT or trichiasis in 12 months, of which 9 (13%) required removal or trimming of eyelashes due to irritation and 2 (2.9%) suffered corneal abrasion." (PMID 39739702, 2024).
urinary system tumors (1 paper, 2024). "The availability of tumor-associated antigens in urinary system tumors, such as prostate stem cell antigen (PSCA), prostate specific membrane antigen (PSMA), and epidermal growth factor receptor (EGFR), makes CAR T cell therapy possible for urinary system tumors." (PMID 38789450, 2024).
urinary tract infection (1 paper, 2026). "Their clinical courses diverged: one EGFR-mutated patient maintained preserved renal function and remained free from urinary tract infection for three years and four months following stent placement, whereas the remaining two patients experienced rapid disease progression and died within months." (PMID 41635341, 2026).
vaginal melanoma (1 paper, 2023). A primary malignant neoplasm of the vagina composed of malignant melanocytes. "In this study, we showed that combinations of selected MET and EGFR inhibitors, crizotinib, foretinib and lapatinib, respectively, act effectively in the two commercially available MM cell lines as well as MM cells isolated from patient's vaginal melanoma." (PMID 37679999, 2023).
Venous malformation (1 paper, 2023). A vascular malformation resulting from a developmental error of venous tissue composed of dysmorphic channels lined by flattened endothelium and exhibiting slow turnover. "Epidermal growth factor receptor (EGFR)/ErbB1 ligand transforming growth factor A (TGFA) is upregulated in venous malformation (VM) and angiomatosis of soft tissue (AST) patient tissue samples." (PMID 37199488, 2023).
ventricular septal defect (1 paper, 2023). The presence of a defect (opening) in the septum that separates the two ventricles of the heart. "Taking some examples, in ventricular septal defects (VSD), lncR-Meg3 was found to be directly targeted by miR-7-5p and significantly inhibited autophagy through EGFR signaling pathway." (PMID 36968595, 2023).
Ventriculomegaly (1 paper, 2016). An increase in size of the ventricular system of the brain. "Overexpression of human HB-EGF further elicits hemorrhage in the subarachnoid space, an increase of VEGF and phosphorylated EGFR in the presence of ventriculomegaly." (PMID 27243144, 2016).
vesicoureteral reflux (1 paper, 2025). Abnormal flow of urine from the urinary bladder back into the ureters. "AFAP1L2 enables SH3 domain binding activity and protein tyrosine kinase activator activity and is involved in the positive regulation of the epidermal growth factor receptor signaling pathway, associated with vesicoureteral reflux and cartilage cancer." (PMID 40251596, 2025).
Vestibular schwannoma (1 paper, 2014). A vestibular schwannoma (also known as acoustic neuroma, acoustic neurinoma, or acoustic neurilemoma) is a benign, usually slow-growing tumor that develops from the VIIIth cranial nerve supplying the inner ear. "Clinical analysis has shown that vestibular schwannomas overexpress ErbB2/3 and that EGFR and its ligand are up-regulated in the majority of NF2-related vestibular schwannomas." (PMID 24393766, 2014). "Lapatinib, which targets EGFR and ErbB-2, is being examined in both a phase 0 study treating vestibular schwannomas (NCT00863122) and a phase II (NCT00973739) trial for its effectiveness in all NF2 related tumor types." (PMID 24393766, 2014).
villous adenoma (1 paper, 2025). An epithelial neoplasm morphologically characterized by the presence of a villous architectural pattern. "In most samples (52.95%), EGFR amplification was observed, which may lead to abnormal activation of the MAPK/PI3K pathways, contributing to increased cell proliferation and oncogenesis; this phenomenon reached 87.5% in villous adenoma patients." (PMID 40919165, 2025).
vitamin A deficiency (1 paper, 2015). Deficiency of vitamin A due to malnutrition, malabsorption, or dietary lack. "Vitamin A deficiency (control) significantly decreased the mRNA expression levels of MUC2, IgA, EGFR, IL-13 and TGF-β in trachea tissue." (PMID 26422233, 2015).
vocal cord polyps (1 paper, 2023). "In a study on laryngeal HNSCC, a higher frequency of strong nuclear EGFR was found in invasive tumors compared to laryngeal dysplasia and vocal cord polyps, and high nuclear EGFR expression levels correlated with worse overall cancer patients’ survival." (PMID 36817764, 2023).
von Hippel-Lindau disease (1 paper, 2022). An autosomal dominant disorder caused by pathogenic variants in the VHL gene, leading to an increased risk of various benign and malignant tumors, including hemangioblastomas, retinal hemangiomas, endolymphatic sac tumors, renal cell carcinoma, and pheochromocytomas. "miR-566 stimulates epidermal growth factor receptor pathway via von Hippel–Lindau disease." (PMID 35053622, 2022).
Wilms renal tumors (1 paper, 2025). "Among the adherent cultures there were five cultures that later turned out to be derived from non-Wilms renal tumors according to reference pathology (2 CMN, 2 CCSK, 1 CN with the typical EGFR-ITD, BCOR-ITD and DICER1 mutations)." (PMID 39740515, 2025).
Zinc deficiency (1 paper, 2022). A deficiency of the essential metal Zinc; an essential cofactor for many enzymes. "In our hands, chronic zinc deficiency led to increased EGFR surface expression, decreased E-cadherin protein expression and increased PD-L1 protein expression." (PMID 35216384, 2022). "Moreover, treating zinc-deficient cells with imatinib, the tyrosine kinase inhibitor, succeeded in reversing the effect of zinc-deficiency-induced EGFR phosphorylation and also reversed the increased PBMC death rate." (PMID 35216384, 2022).